ICAM2 (intercellular adhesion molecule 2)
Diseases named in the same sentence as ICAM2 in open-access papers (continued):
Sharing a sentence is not in itself a finding about the gene and the disease.
Obesity (2 papers, 2022 to 2023). Accumulation of substantial excess body fat. "After binding with its ligand intercellular adhesion molecule 2 (ICAM-2), P9 promotes thermogenesis and improves obesity and glucose homeostasis by activating the GLP-1R signaling pathway and interleukin-6 (IL-6)." (PMID 37040299, 2023). "In the case of P9, glucose homeostasis and obesity reduction are related to the interaction of P9 with intercellular adhesion molecule 2 (ICAM-2) and an increase in type 2 macrophages (M2) in an IL-6 dependent pathway." (PMID 35874661, 2022).
oral cancer (2 papers, 2008 to 2016). "To further our understanding of the function of ICAM2, we stably knocked down ICAM2 with siRNA vectors targeting ICAM2 in HSC4 oral cancer cells, which express high levels of endogenous ICAM2." (PMID 27556181, 2016). "SAS and Ca9-22 oral cancer cells were used; in both cells, endogenous ICAM2 expressions were at negligible levels." (PMID 27556181, 2016). "So, we evaluated whether radiosensitivity of oral cancer cells is determined by cellular ICAM2 by using siRNA targeted against ICAM2 gene." (PMID 18349842, 2008).
periodontitis (2 papers, 2022). An acute or chronic inflammatory process that affects the tissues that surround and support the teeth. "CSF3, ICAM2, and MMP7 serve as diagnostic and prognostic biomarkers for periodontitis." (PMID 36457739, 2022).
Arthritis (1 paper, 2016). Inflammation of a joint. "In conclusion, recruitment of leukocytes into the joints and the ensuing arthritis in the K/BxN STA model seem to be dependent on the expression of LFA-1 on leukocytes, especially neutrophils, and the binding to its ligands, ICAM-1, ICAM-2, and JAM-A, expressed on the activated vascular endothelium." (PMID 27313578, 2016). "Moreover, blockade of LFA-1 with an anti-LFA-1 mAb reduced the already ongoing inflammation, and functional blockade of its counter-receptors, ICAM-1, ICAM-2, and JAM-A, provided a reduction, but not complete amelioration, of arthritis." (PMID 27313578, 2016).
bladder cancers (1 paper, 2016). "Furthermore, decrease in ICAM2 expression was shown to be a poor prognostic factor in human breast, lung, and bladder cancers." (PMID 27556181, 2016).
colitis (1 paper, 2023). Inflammation of the colon. "Lysozyme-expressing CD102+ (ICAM2)+ macrophages are recruited in a CCR2- and antibiotic-independent manner to the colon in DSS-induced colitis and have been proposed to promote intestinal repair." (PMID 37876927, 2023).
colorectal cancer (1 paper, 2016). A primary or metastatic malignant neoplasm that affects the colon or rectum. "Additionally, ICAM2 silencing enhanced FBS-induced phosphorylation of ERK in HCT15 colorectal cancer cells." (PMID 27556181, 2016).
cyst (1 paper, 2022). A sac-like closed membranous structure that may be empty or contain fluid or amorphous material. "Both the ICAM2 and Claudin5 levels were higher in the endometrial fragments in cyst fluid than in the corresponding ectopic tissue." (PMID 35907907, 2022). "We detected ICAM2 and Claudin5 expression in the endometrial fragments in cyst fluid and ectopic lesions by IHC." (PMID 35907907, 2022).
diabetes (1 paper, 2015). "Although the Icam1 gene is essential for diabetes development in NOD the presence of this deletion shows that the Icam2 gene in the Dvs substrain is dispensable for diabetogenesis." (PMID 25740934, 2015).
E. coli infection (1 paper, 2016). "It has been shown that endothelial surface expression of ICAM-1 and CD44 is significantly elevated upon E. coli infection but expression of ICAM-2, VCAM-1 or E-selectin in pulmonary endothelial cells is not affected." (PMID 27657497, 2016).
endotoxemia (1 paper, 2024). "ICAM-2, on the other hand, decreased during endotoxemia in our study, which may have contributed to increased vascular permeability; however, the change in the interaction between ICAM-2 and neutrophils for adhesion was not obvious." (PMID 38348045, 2024).
eosinophilia (1 paper, 2020). "However, blocking ICAM-2 in vivo during IL-33-induced airway inflammation did not affect either the numbers of pulmonary ILC2s or BAL eosinophilia, suggesting that ICAM-2 — either on ILC2s or other cells — does not affect ILC2 accumulation in the lungs, at least sufficiently." (PMID 33193309, 2020).
influenza infection (1 paper, 2022). "Thus, all major components of anti-viral humoral immunity are normally elicited in lung draining LNs deficient in ICAM-1 and ICAM-2 during a primary influenza infection, resulting in normal IgG dependent viral clearance." (PMID 36895258, 2022). "Our results rule out that influenza infection elevates ICAM-1 expression on alveolar capillaries and suggests that ICAM-1 and ICAM-2 do not serve as the primary ligands for neutrophil margination at steady state conditions." (PMID 36895258, 2022).
injury (1 paper, 2018). Damage inflicted on the body as the direct or indirect result of an external force, with or without disruption of structural continuity. "What’s more, inflammation-related factors including CRP, ICAM-2, and MMP-9 were also elevated, suggesting that after traumatic brain injury, the innate immune system was activated, then the inflammatory factors damaged the blood–brain barrier and were released into the blood." (PMID 30766469, 2018).
ischemia (1 paper, 2011). A hypoperfusion of the BLOOD through an organ or tissue caused by a PATHOLOGIC CONSTRICTION or obstruction of its BLOOD VESSELS, or an absence of BLOOD CIRCULATION. "TNFα and IL-1 have been shown to cause up-regulation of E-selectin, ICAM-1, ICAM-2, and VCAM-1 on cerebral endothelial cells and the induction of such adhesion molecules may explain the elevation of TNFα and IL-1 levels after ischemia increases neutrophil infiltration." (PMID 22196138, 2011).
lentivirus infection (1 paper, 2022). Virus diseases caused by the Lentivirus genus. "We next stably overexpressed ICAM2 in RA‐FLSs with lentivirus infection." (PMID 36536495, 2022).
leptospirosis (1 paper, 2014). A contagious bacterial infection caused by spirochetes of the genus Leptospira. "ICAM-2, along with other adhesion molecules E-selectin and VCAM, has been shown to be highly expressed in lungs of patients that succumbed to leptospirosis, and is thought to participate in recruitment of inflammatory cells and release of effectors at the infected site." (PMID 24498454, 2014).
lung disease (1 paper, 2021). "However, only modestly increased levels of ICAM-1 and ICAM-2 expression were found on inflamed bronchial epithelium from patients with COPD (another lung disease characterized with neutrophilic-driven inflammation) compared to normal lung." (PMID 34484188, 2021).
Lymphatic Metastasis (1 paper, 2023). Transfer of a neoplasm from its primary site to lymph nodes or to distant parts of the body by way of the lymphatic system. "Although no statistical significance was detected between ICAM2 expression levels in lymphatic metastasis-positive and negative patients, patients with lymphatic metastasis had lower levels of ICAM2 expression than those without lymphatic metastasis." (PMID 37759298, 2023).
parasitemia (1 paper, 2022). "We compared expression of ICAM1, ICAM2, and VCAM1 proteins in the vasculature of the brain at the first peak of parasitemia in both strains, by ex-vivo microscopy." (PMID 35787830, 2022). "Mean fluorescent intensity of ICAM1, ICAM2, and VCAM in the brain endothelium in non-infected mice and in mice infected with T. congolense 1/148 or IL3000, at the first peak of parasitemia, and respective representative images." (PMID 35787830, 2022).
pneumonitis (1 paper, 2024). An inflammatory process affecting the lung parenchyma. "The relative early timepoint at which the expression of the inflammatory marker ICAM-2 is upregulated suggests that ICAM-2 plays a particularly pivotal role in the acute pneumonitis-associated phase of RILD that occurs between 4 and 16 weeks post-irradiation of the thorax in C57BL/6 mice." (PMID 39518030, 2024).
proliferative diabetic retinopathy (1 paper, 2020). Advanced retinopathy due to diabetes mellitus characterized by the formation of new vessels in the retina. "In particular, increased expression of cell adhesion molecules such as VCAM1, ICAM1, and ICAM2 is a feature of proliferative diabetic retinopathy (PDR), where they increase recruitment of leukocytes to the endothelium and disrupt blood flow, a process termed leukostasis." (PMID 32811565, 2020).
pterygium (1 paper, 2025). A wedge-shaped fibrovascular lesion arising from the bulbar conjunctiva and extending to the cornea. "There was a significant positive correlation between pterygium grade, ICAM2 protein expression (p = 0.0398), and ICAM3 immunohistochemical score (p = 0.0138)." (PMID 39991572, 2025). "ICAM2 and ICAM3 protein expressions were also significantly increased in pterygium tissues (p = 0.0116 and p = 0.0252, respectively)." (PMID 39991572, 2025). "The results showed a significant increase in ICAM2 and ICAM3 gene expression in pterygium tissues (p = 0.0018 and p = 0.0023, respectively)." (PMID 39991572, 2025).
Sepsis (1 paper, 2025). Sepsis is defined as life-threatening organ dysfunction caused by a dysregulated host response to infection. "Using this model, we identified five key genes for constructing the sepsis diagnostic model: SHKBP1, ICAM2, CTSD, SNX3, and SLC22A4." (PMID 41445732, 2025). "We established a diagnostic model based on five key genes(SHKBP1,ICAM2,CTSD,SNX3, and SLC22A4), and Kaplan-Meier survival analysis revealed that SHKBP1 was significantly correlated with both the diagnosis and prognosis of sepsis." (PMID 41445732, 2025).
synucleinopathy (1 paper, 2025). A neurodegenerative disease that is characterized by the abnormal accumulation of aggregates of alpha-synuclein protein in neurons, nerve fibers or glial cells. "Instead, we demonstrated the suppression of other microglial mobility/phagocytosis-associated genes such as Icam2, Acta2, Fos, Fosb, Egr1, Lamb2 and Tpm2 in both synucleinopathy patients and the animal model." (PMID 41258081, 2025).
vasculitis (1 paper, 2023). "ITGB2 (CD18) a receptor for ICAM1, ICAM2, ICAM3, and ICAM4, is a potential mechanistic biomarker for vasculitis." (PMID 38274452, 2023).
viral infection (1 paper, 2022). "These staining results suggest that the entry of virus specific effector T cell egressing the MedLNs on their way to the bronchial mucosa during viral infection, likely involves VCAM-1 rather than ICAM-1 and ICAM-2 mediated adhesions." (PMID 36895258, 2022). "Furthermore, during viral infection, the presence of ICAM-1 or of ICAM-2 on all lung capillaries is also not required for neutrophil or NK cell emigration into the alveolar space." (PMID 36895258, 2022).
tumor (38 papers, 2007 to 2026). "Therefore, in order to identify domains of ICAM-2 that contribute significantly to its function in tumor cells, we generated four ICAM-2 constructs, encoding glycosylation site variants (gsv) of this protein." (PMID 23714211, 2013). "Transduction of ICAM-2 by intratumoral injection significantly inhibited tumor growth in subcutaneous gastric tumors." (PMID 40071851, 2025). "Together with CXCL17, ICAM-2 promotes pancreatic tumor infiltration of dendritic cells, which increases specific lysis of tumor cells by cytotoxic T cells." (PMID 38786066, 2024). "After 10 weeks of mammary fat pad injection, 1 × 103 and 1 × 102 ICAM2-overexpressing groups exhibited 100% and 50% of tumor-initiation ability, respectively, compared with control groups, which already had 50% and 0% tumor-initiation ability." (PMID 37620448, 2023). "Further tests in 15 tumor tissues and matched adjacent normal tissues (selected randomly from the preceding forty-five cases) showed that ICAM2 protein expression level was decreased in tumor tissues." (PMID 37759298, 2023). "In summary, this study demonstrates the tumor-suppressive role of ICAM2 and its correlation with RDX in GC." (PMID 37759298, 2023). "In this study, the high levels of ICAM2 promoted leptomeningeal-tropic metastasis in vivo and increased the number of tumor cells adhering to the BCB and trans-BCB migration abilities in vitro." (PMID 37620448, 2023). "In xenograft tumor models, Overexpression of RDX in MGC803 cells erased ICAM2-induced growth rate and tumor weight differences." (PMID 37759298, 2023). "Consistent with results from in vitro experiments and those from the TCGA database, ICAM2 protein levels were lower in GC tissues compared to adjacent non-tumor tissues." (PMID 37759298, 2023). "Consistent with the findings in the subcutaneous transplantation tumor model, ICAM2 overexpression significantly decreased lung metastatic lesions originating from MGC803 cells." (PMID 37759298, 2023). "A tumor-initiation ability of 1 × 103 ICAM2-overexpressing groups was detected in the second week after injection, whereas the vector control groups were undetectable till the third week after injection." (PMID 37620448, 2023). "Together, these results indicated that the LeptoM3 and BCB adhesion cells expressed higher stemness markers CD44, CD133, and EPCAM and lower CD24 and the overexpression of ICAM2 promoted sphere formation and tumor initiation." (PMID 37620448, 2023). "Considering that ICAM2 is involved in tumor development, we explored the mechanisms by which ICAM2 inhibited cell growth and metastasis." (PMID 37759298, 2023). "It was found that the expression of intercellular adhesion molecule-2 (ICAM-2) suppresses tumor dissemination in a murine model of metastatic NB." (PMID 27686492, 2016). "It was found that intercellular adhesion molecule-2 (ICAM-2) completely suppressed disseminated tumor development in vivo in a murine model of metastatic NB." (PMID 24904828, 2014). "The data show that ICAM-2-mediated redistribution of actin fibers and inhibition of tumor cell motility depended on an intact intracellular domain." (PMID 18978946, 2008). "ICAM-2 and CEACAM1 are also similar in that their association with the actin cytoskeleton and their suppression of tumor growth or metastasis (for CEAMCAM1 or ICAM-2, respectively) depend on an intact intracellular domain [37 and data herein]." (PMID 18978946, 2008). "Namely, tumor cells exhibiting histologic evidence of ganglionic differentiation were the predominant subset of ICAM-2-positive cells." (PMID 18978946, 2008).
tumor (continued). "Co-incident with observed ICAM-2-mediated redistribution of actin fibers was an inhibition of tumor cell motility, as assessed with two types of in vitro assays: scratch (wound) assays and modified Boyden chamber invasion assays." (PMID 18978946, 2008). "ICAM-2 inhibition in the tumor promoted anti-tumor response in colon carcinomas mouse models." (PMID 40071851, 2025). "Of note, ICAM-2 is specifically reported as increasing anti-tumor immunity." (PMID 40071851, 2025). "ICAM-2 also seems to play an important role in NK cell clearance of tumor cells." (PMID 38786066, 2024). "On the other hand, TECs also might contribute to lymphocyte migration into the tumor via ICAM1/ICAM2-(ITGAL + ITGB2) interactions with T/NK cells." (PMID 39093451, 2024). "Additionally, in a murine model of breast cancer, ICAM-2 upregulation in dendritic cell vaccine therapy correlated with improved tumor control, which interestingly exhibited lower ICAM-1 expression." (PMID 38786066, 2024). "ICAM2 also promoted the transmigration of tumor cells across the BCB." (PMID 37620448, 2023). "Moreover, analysis of the transcriptome sequencing data obtained from the TCGA database revealed that ICAM2 was downregulated in 10 different tumor types." (PMID 37759298, 2023). "To investigate whether tumor cells accumulated on the choroid plexus, we determined the expression of the ICAM2 and ICAM1 proteins." (PMID 37620448, 2023). "Finally, tumor initiation was evaluated in mice injected with ICAM2-overexpressing cells and vector control cells with mammary fat pad injection; the following tumor-initiation ability was detected using IVIS every week." (PMID 37620448, 2023). "Furthermore, high levels of ICAM2 in TNBC cells enhanced tumor cell adhesion to the choroid plexus epithelial cells of the BCB." (PMID 37620448, 2023). "We investigated whether pretreatment with anti-ICAM2 neutralizing antibodies in 1 × 103 LeptoM3 cells to mimic blocking the circulating tumor cells after surgical resection could be applied as preventive care for LM in TNBC." (PMID 37620448, 2023). "Several reports state that ICAM2 functions as a tumor suppressor." (PMID 27556181, 2016). "Because it is well documented that glycosylation facilitates essential steps in tumor progression and metastasis, we investigated whether the glycosylation status of ICAM-2 affected the phenotype of NB cells." (PMID 23714211, 2013). "Finally, the finding that ICAM-2 expression inhibited tumor cell motility in scratch and modified Boyden chamber invasion assays in vitro merits further discussion." (PMID 18978946, 2008). "In tumor cells in particular, constitutive activation of proteins up- or down-stream of the bidirectional signals mediated by CAMs might also affect ICAM-2 function and cell phenotype." (PMID 18978946, 2008). "Thus, a primary tumor exhibits heterogenous TNBC cells with high levels of ICAM2." (PMID 37620448, 2023). "Recently, we demonstrated a previously unknown function for ICAM-2 in tumor cells." (PMID 23714211, 2013). "The effect of glycosylation of ICAM-2 on tumor cell function is unknown." (PMID 23714211, 2013). "However, unlike fully-glycosylated ICAM-2, glycosylation site variants did not completely suppress disseminated tumor development." (PMID 23714211, 2013). "However, the functional role of ICAM2 in tumor progression and metastasis remains unclear." (PMID 37620448, 2023). "Activated platelet membrane nanovesicles, which retain almost all of the platelet-proteins, target tumor tissues through P-selectin and CD44, and mediate neutrophil recruitment through P-selectin, ICAM-2, and CCL5." (PMID 36034656, 2022). "The results indicated that the expression of tumor cell-derived VEGFA, IGFBP3, EFNA1, EFNB1, IGF2, PDGFA and stroma-derived Angpt2, Cdh5, Esam, Esm1, Icam2, and Tie1 was statistically correlated with that of Pecam1 and elevated in p-EMT TW2.6 tumors." (PMID 34869001, 2021).